MIR1185-1 (microRNA 1185-1)
Synonyms: hsa-mir-1185-1; MIRN1185-1; mir-1185-1
Gene: MicroRNA gene on chromosome 14 (101,042,977 to 101,043,062, forward strand). Ensembl gene ENSG00000221525.
Gene Ontology:
Biological process: miRNA-mediated post-transcriptional gene silencing
Cellular component: RISC complex
Homologues: Orthologues: chimpanzee ptr-mir-1185-1 (100% identical), dog MIR1185 (93% identical), macaque mml-mir-1185-1 (91% identical). Paralogues in human: MIR1185-2 (98% identical), MIR539 (65% identical), MIR494 (64% identical), MIR381 (63% identical), MIR487A (63% identical), MIR154 (62% identical), MIR323A (62% identical), MIR487B (62% identical), MIR323B (57% identical), MIR496 (57% identical), MIR410 (55% identical), MIR377 (52% identical), and 4 more.